BDNF (brain derived neurotrophic factor)
Diseases named in the same sentence as BDNF in open-access papers (continued):
Sharing a sentence is not in itself a finding about the gene and the disease.
psychiatric disorder (continued). "Several studies analyzed BDNF rs6265 polymorphisms in psychiatric disorders." (PMID 25587209, 2014). "Thus, the observed differences in BDNF between populations have implications for interpreting the conflicting association literature for psychiatric disorders." (PMID 23593198, 2013). "We hypothesised that other genes functionally related to BDNF could also be implicated in cognition and psychiatric disorders." (PMID 22539971, 2012). "One mechanism by which nicotine may influence the incentive salience of non-drug-associated cues is through brain-derived neurotrophic factor (BDNF), a protein that modulates synaptic plasticity and has been associated with psychiatric disorders, behavioral responses, and drug abuse." (PMID 31315660, 2019). "Dysregulated signaling of brain-derived neurotrophic factor (BDNF), a member of the neurotrophin family of growth factors important for proper neurodevelopment as well as higher cognitive functioning, has been implicated in the etiology of several psychiatric disorders." (PMID 31777665, 2019). "The authors suggested that dysregulation of corticostriatal BDNF expression, along with respective changes in hippocampus, might contribute to permanent alterations in brain functions leading to increased susceptibility to psychiatric disorders." (PMID 24999483, 2014). "The microbiota modulates neurobiological systems relevant to psychiatric disorders, including brain-derived neurotrophic factor (BDNF) signaling, serotonergic neurotransmission, immune function, and hypothalamic–pituitary–adrenal (HPA) axis regulation." (PMID 41598300, 2026). "Child maltreatment has also been found to decrease plasma BDNF protein and increase methylation at salivary and plasma-derived BDNF, which intersects with presentation of psychiatric disease." (PMID 40770493, 2026). "Associated with various mental illnesses, neurotrophins are the most studied subgroup of neurotrophic factors, a family including the nerve growth factor NGF, the brain-derived neurotrophic factor (BDNF), neurotrophin 3 (NT3) and neurotrophin 4 (NT4)." (PMID 40869374, 2025). "A systematic review and meta-analysis of clinical trials with patients with psychiatric disorders reported a significant increase in BDNF levels in individuals treated with probiotic strains, who also showed symptomatic reduction." (PMID 40342368, 2025). "These categories are presented here as a guide for translation of the BDNF research into precision medicine and to provide perspective components in unmet needs for neurological and psychiatric disorders." (PMID 40362507, 2025). "The vocabulary and discourses surrounding integrated synergistic treatment approaches currently constructs the next generation of neurotherapeutics advancing BDNF as a central underpinning axis across neurodegenerative and psychiatric disorders." (PMID 40362507, 2025). "Neurotrophin reduction, including BDNF, is involved in developing various CNS diseases, including neurodegenerative and psychiatric disorders." (PMID 40807615, 2025). "The advancements lay the groundwork for further exploration of BDNF’s potential viability as a biomarker in both neurodegenerative and psychiatric disorders, including use for early diagnosis, tracking disease progression, and precision therapy." (PMID 40362507, 2025). "BDNF is a neurotrophin that modulates brain plasticity, with research showing its effects on psychiatric disorders." (PMID 40722728, 2025). "The next section explores BDNF and its role in stress resilience, psychiatric disorders, and new therapeutic directions in mental health." (PMID 40362507, 2025). "Abnormal expression and signaling of BDNF relates to a relatively large cross section of (neuro)psychiatric disorders, from developmental, and psychiatric, to neurodegenerative categories." (PMID 40362507, 2025).
psychiatric disorder (continued). "Neurotrophic factors, particularly brain-derived neurotrophic factor (BDNF), play a crucial role in the long-term decline in neuronal plasticity associated with mental illness." (PMID 40427467, 2025). "Another biochemical parameter that is emphasized in psychiatric diseases is brain-derived neurotrophic factor (BDNF)." (PMID 41210122, 2025). "With BDNF being one of the most profound compounds studied in psychiatric disorders, it would be beneficial to identify nutritional interventions that impact its presence in the body." (PMID 40722728, 2025). "BDNF has been examined in several psychiatric disorders and has been proposed as a putative biomarker in several disorders, including SUD." (PMID 41210122, 2025). "Brain-derived neurotrophic factor (BDNF) plays a key role in neuronal growth and function, with its dysregulation being linked to various psychiatric disorders." (PMID 39997339, 2025). "The broad actions of BDNF make it an appealing target for drug development for many different neurological and psychiatric disorders." (PMID 40362507, 2025). "In particular, impairments in brain-derived neurotrophic factor (BDNF) production in psychiatric diseases have been shown in experimental preclinical studies." (PMID 40867635, 2025). "This indicated that BDNF Val66Met polymorphism might have differential effects on cognitive functions in the presence of psychopathology and could modulate the effect of age and severity of psychiatric disorders on cognitive performance, possibly through BDNF methylation." (PMID 41009553, 2025). "Collectively these findings implicate BDNF as a mechanistic link between chronic stress and the development of both physical and mental illness and warrants investigation as a potential target for therapy." (PMID 40362507, 2025). "Clinical studies have found associations between decreased levels of brain-derived neurotrophic factor (BDNF) and increased inflammatory markers, which are linked to the onset of depressive symptoms and various psychiatric disorders." (PMID 38911040, 2024). "The prevalence of childhood adversity and stressful life events in AN patient further supports the role of BDNF as an intermediary factor in the relationship between life stress and psychiatric disorders." (PMID 39203753, 2024). "This implies the possible existence of different subtypes or biotypes within psychiatric disorders with different modes of expression and roles of BDNF within their etiopathological mechanisms." (PMID 39456983, 2024). "Intriguingly, this proBDNF/BDNF ratio inversion aligns with the progression of adolescence, a period with an inherently elevated risk for the onset of mental illness." (PMID 38177347, 2024). "Changes in plasma BDNF levels vary, showing either increases or decreases in different psychiatric disorders." (PMID 39203753, 2024). "Brain-derived neurotrophic factor (BDNF) is a potential biomarker of response to treatment in psychiatric disorders." (PMID 39456983, 2024). "BDNF is crucial for the plasticity of glutamatergic and gamma aminobutyric acid (GABA)ergic synapses and is intimately linked to severe mental illnesses." (PMID 38469409, 2024). "A lot of CREB target genes have been demonstrated to be closely related to psychiatric disorders, such as BDNF, protein kinase B (Akt), and glycogen synthase kinase 3β (GSK3β)." (PMID 38372284, 2024). "The subsequent research revealed that BDNF plays a crucial role in promoting the survival and growth of neurons in the central nervous system and that BDNF disruption is involved in various neurological and psychiatric disorders." (PMID 39125882, 2024). "Variations in BDNF levels have been observed across a range of psychiatric disorders, with its regulatory role intimately connected to both the underlying pathophysiology and therapeutic interventions of these ailments." (PMID 38988887, 2024).
psychiatric disorder (continued). "When these disorders co-occur with CUD, referred to as dual diagnosis, we observe distinct neurotrophin fluctuations, emphasizing the impact of psychiatric disease on central BDNF production." (PMID 38177347, 2024). "Overall, BDNF‐based therapeutic approaches hold significant potential for treating various neurological and psychiatric disorders." (PMID 39648800, 2024). "Quantitative assessment of BDNF and pro-BDNF from blood serum is a common strategy employed to diagnose various psychiatric disorders." (PMID 38125619, 2024). "BDNF dysregulation has emerged as a key factor in several neurological and psychiatric disorders, offering valuable insights into the potential therapeutic dimensions of these conditions." (PMID 39568824, 2024). "TrkB-D5 is considered as a favorable target for neurological and psychiatric disorder agonists, which bind to this TrkB domain to mimic the binding of Brain-Derived Neurotrophic Factor (BDNF)." (PMID 39274839, 2024). "This study has uncovered significant associations between rs6265 in BDNF, rs1800955 in DRD4, and psychiatric disorders in a general cohort of patients with mental illnesses compared to the controls." (PMID 38397229, 2024). "The deficit of CREB/BDNF signalling impairs neurodevelopment and contributes to psychiatric disorders." (PMID 38372284, 2024). "The collaboration between BDNF, platelets, and psychiatric disorders presents a promising avenue for understanding and potentially treating these complex mental health conditions." (PMID 39568824, 2024). "Given the biological importance of NTF genes, such as BDNF, which appears to have a relationship with psychiatric diseases, investigation of the impacts of E-cig exposure on NTF expression with a larger cohort is important to further clarify potential effects." (PMID 38540381, 2024). "The involvement of BDNF in the pathogenesis of psychiatric disorders and responses to therapy has been widely demonstrated." (PMID 38397229, 2024). "The BDNF/pro-BDNF ratio at the peripheral and central levels is assumed to be a determinant of psychiatric disorders." (PMID 39430530, 2024). "The ratio of brain-derived neurotrophic factor brain derived neurotrophic factor(BDNF) and pre-BDNF can monitor the therapeutic progression of psychiatric disorders." (PMID 38173021, 2024). "Nevertheless, extensive previous research on the topic of BDNF and psychiatric disorders adds to the relevance of these findings." (PMID 36766691, 2023). "Recent data suggest a correlation between BDNF signaling deficits and some major brain diseases, including psychiatric disorders such as schizophrenia, major depressive disorder (MDD), and BD." (PMID 37626577, 2023). "BDNF is involved in the plasticity of numerous neurons throughout various brain regions and significantly impacts stress-related psychiatric disorders." (PMID 37780709, 2023). "BDNF has been widely studied in psychiatric disorders and its possible roles in the pathophysiology of them were discussed in the last two decades." (PMID 36641432, 2023). "A consistent body of evidence demonstrates the clinical values of NGF and BDNF changes in serum by showing their correlation with the insurgence, severity, and response to treatments in neurological, immune, and psychiatric diseases." (PMID 37175781, 2023). "The potential clinical relevance of BDNF arises from the evidence of declining BDNF concentrations in numerous psychiatric disorders, aging, and neurodegenerative diseases." (PMID 37993570, 2023). "The relationship between BDNF concentration and cognitive performance has been described in several neurodegenerative and psychiatric disorders." (PMID 36936159, 2023). "Several intriguing reports assessing epigenetic endpoints in serum or post-mortem samples from humans suffering from other neurological and psychiatric disorders also observed the differential methylation of BDNF promoters." (PMID 37626771, 2023).
psychiatric disorder (continued). "BDNF methylation was excluded because the role of this parameter as a suitable biomarker for psychiatric disorders is not well understood." (PMID 37895349, 2023). "BDNF binds preferentially to the TrkB receptor, and BDNF/TrkB system dysfunction correlates with pathophysiology in psychiatric disorders." (PMID 36614066, 2022). "Clinically, the levels of BDNF pro-peptide are altered in individuals with neurodegenerative or psychiatric disorders, but the trends are disease and sex-specific." (PMID 35887357, 2022). "The diverse presence and activity of BDNF indicate its potential role in the pathogenesis, progression and treatment of both neurological and psychiatric disorders." (PMID 36158555, 2022). "Neurotrophins, particularly BDNF and nerve growth factor (NGF), are another type of cytokines associated with cognitive impairment in psychiatric disorders." (PMID 36406755, 2022). "Many studies have focused on the alternation of the peripheral BDNF level in different situations and reported BDNF changes in neurodegenerative disorders, brain insults, and psychiatric disorders." (PMID 35287688, 2022). "Brain-derived neurotrophic factor (BDNF) and its associated receptor, tropomyosin receptor kinase B (TrkB), have come under increasing scrutiny for their role in several psychiatric disorders including PTSD." (PMID 36311515, 2022). "Stress is an environmental factor well-known for its notorious part in the development of psychiatric disorders, possibly through altering the expression of stress-related genes, such as BDNF." (PMID 35448545, 2022). "In contrast, the cerebellum of these groups with psychiatric disorders contained significantly lower levels of BDNF pro-peptide compared to controls." (PMID 35887357, 2022). "Such an importance of BDNF in synaptic regulation prompts scientist to approach its potential as a candidate to treat psychiatric disorders in which the dysregulation of synaptic function occurs." (PMID 35887075, 2022). "Nevertheless, we excluded subjects with major psychiatric disorders, known to have a potential impact on S100B and BDNF." (PMID 35910248, 2022). "The brain-derived neurotropic factor (BDNF) gene may be a specific target gene of interest that has shown to be susceptible to epigenetic regulation following stressful exposures and to be significantly associated with increased risk of psychiatric disorders, including anxious symptomatology." (PMID 35911240, 2022). "Reduced BDNF protein were detected in the hippocampus both in postmortem brain samples from psychiatric disorder patients who had committed suicide, and in depressed rats." (PMID 36686688, 2022). "The diverse presence of BDNF leads to its important involvements in multiple neurological and psychiatric disorders." (PMID 36158555, 2022). "BDNF has a complex relation to the pathophysiology and symptomatology of immune-related diseases, regulating inflammation, circadian rhythms, psychiatric disorders, and the gut–brain axis." (PMID 36294343, 2022). "Brain-derived neurotrophic factor (BDNF) is a key modulator of neuroplasticity and has an important role in determining the susceptibility to severe psychiatric disorder with a significant neurodevelopmental component such as major psychoses." (PMID 36552127, 2022). "Promising results were indeed observed for genetic BDNF upregulation or exogenous administration using a multitude of murine models of neurological and psychiatric diseases." (PMID 35955546, 2022). "Many studies have revealed that BDNF is involved in chronic stress and psychiatric disorders, such as bipolar disorder, mood disorders, and schizophrenia." (PMID 34827728, 2021). "Changes in BDNF expression have been identified in studies of conditions such as stress, psychiatric disorders, and neurodegenerative disorders." (PMID 34576126, 2021). "It has been shown that the levels of BDNF are reduced in the brain of patients with neurodegenerative and psychiatric disorders." (PMID 34966254, 2021).
psychiatric disorder (continued). "Exposure to chronic stress can alter BDNF expression, which has also been found abnormal in psychiatric disorders, such as MDD and PTSD." (PMID 33578758, 2021). "Our findings highlight targeted activation of neurotrophin signalling pathways with BDNF mimetic drugs as a genetically informed therapeutic approach for rescuing behavioural abnormalities in psychiatric disorder." (PMID 33597718, 2021). "Studies have shown that a lack of BDNF can lead to impairment of memory and cognitive functions, indicating that BDNF plays an important role in mental illness and neurodegenerative diseases." (PMID 35194435, 2021). "Single nucleotide polymorphisms (SNPs) in the BDNF gene, such as rs6265, rs12273539, rs10835210, and rs2030324, have previously been thought to affect different psychiatric disorders and/or serum levels of BDNF in chronic patients with SZ13–16." (PMID 34625629, 2021). "This is supported by the fact that stress-related psychiatric disorders such as MDD and PTSD have been linked repetitively to BDNF, synaptic plasticity and dysregulation in GR signaling." (PMID 34330919, 2021). "BDNF plays an important role in synaptic plasticity and memory, and its levels are reduced in the brains of patients with neurodegenerative and psychiatric disorders." (PMID 34966254, 2021). "Strong biomarker candidates such as brain-derived neurotrophic factor (BDNF) and transcription factor 4 (TCF4) gene variants are unsuitable due to their involvement in other major psychiatric disorders." (PMID 34829325, 2021). "Being highly prevalent (30–50% of carriers in the U.S. and some European countries), this SNP likely plays an important role in BDNF function when related to the development of several neurodegenerative and psychiatric disorders, including MDD." (PMID 33578758, 2021). "In contrast, chronic exposure to dexamethasone can suppress BDNF-induced glutamate release, which affects the processes of long-term memory consolidation and developing mental illnesses." (PMID 33152026, 2020). "Further evidence suggests a relationship between stress exposure and epigenetic regulation of BDNF promoter IV with the development of psychiatric disorders." (PMID 33096634, 2020). "Since BDNF has been mostly studied in animal models and the few human studies are in the context of pathological conditions (e.g., mood and psychiatric disorders) or based on its genes, homeostatic information is very limited." (PMID 32399021, 2020). "In this review, we summarize current research regarding how different types of stressors influence BDNF expression in specific brain regions and their relationship with various mental illnesses." (PMID 32085670, 2020). "Distinguishing the effects of these factors is necessary for clarification of the relationship between stress and BDNF, which will further facilitate the clinical treatment of stress-induced mental illness." (PMID 32085670, 2020). "Treatment with therapeutic drugs for psychiatric disorders reduces blood IL-6 and corticosterone levels, increases BDNF expression, and alleviates neuropsychiatric disorders." (PMID 32158447, 2020). "The beneficial effects of BDNF in chronic neurological diseases and psychiatric disorders have been extensively reviewed in recent years." (PMID 32399020, 2020). "The brain-derived neurotrophic factor (BDNF) regulates activity-dependent synaptic plasticity and psychiatric disorders, while CREB regulates genes related to neuronal differentiation, synaptic plasticity, learning, and memory." (PMID 33585279, 2020). "Thus, considering that these parameters are determinant for protein interactions and, consequently, protein function; the alterations observed throughout the MD analyses may be related to the functional impairment of BDNF upon V66M mutation, as well as its involvement in psychiatric disorders." (PMID 30998730, 2019).